GPR108 (G protein-coupled receptor 108)
Description:
May play a role in intracellular immune modulation by activating NF-kappaB response and attenuating Toll-like-receptor response. (Microbial infection) Plays an essential function in adeno-associated virus (AAV) transduction across multiple serotypes except AAV5. May play a critical role in mediating the endosomal virus escape or in the AAV virions trafficking from endosomes to the nucleus.
Synonyms: LUSTR2
Tractability: Antibody: UniProt predicts a signal peptide or a membrane-spanning region. PROTAC: ubiquitination databases record sites on it; its protein half-life has been measured.
Gene: Protein-coding gene on chromosome 19 (6,729,914 to 6,737,606, reverse strand). Ensembl gene ENSG00000125734.
Subcellular location: Golgi apparatus, cis-Golgi network membrane; Golgi apparatus, trans-Golgi network membrane; Golgi apparatus membrane
Subcellular location (Human Protein Atlas): Golgi apparatus; Vesicles
Gene Ontology:
Molecular function: protein binding
Biological process: negative regulation of toll-like receptor signaling pathway; regulation of immune response
Cellular component: Golgi apparatus; Golgi membrane; trans-Golgi network; cis-Golgi network membrane; membrane
Genetic constraint (gnomAD): Loss-of-function variants: 59 observed, 72.16 expected, observed/expected ratio (o/e) 0.82, 90% interval 0.66 to 1.02. The upper end of that interval is the gene's LOEUF score, 1.02, which puts it in group 4 of 6, group 1 being the genes least tolerant of losing a copy. Missense variants: 664 observed, 704.58 expected, observed/expected ratio (o/e) 0.94, 90% interval 0.88 to 1. Synonymous variants: 309 observed, 286.44 expected, observed/expected ratio (o/e) 1.08, 90% interval 0.98 to 1.18.
Homologues: Orthologues: chimpanzee GPR108 (99% identical), macaque GPR108 (95% identical), pig GPR108 (87% identical), guinea pig GPR108 (83% identical), mouse Gpr108 (83% identical), dog GPR108 (81% identical), rat Gpr108 (79% identical), Drosophila melanogaster CG12121 (42% identical), zebrafish gpr108 (40% identical), Caenorhabditis elegans C15H9.5 (31% identical), Caenorhabditis elegans C52B9.4 (15% identical), Drosophila melanogaster CG17660 (14% identical). Paralogues in human: GPR107 (48% identical), TMEM87A (16% identical), TMEM87B (15% identical).
Diseases named in the same sentence as GPR108 in open-access papers:
GPR108 is named in the same sentence as 7 diseases in open-access papers, as found by Europe PMC text mining. Sharing a sentence is not in itself a finding about the gene and the disease. The quoted sentences say what the papers report.
colorectal cancer (1 paper, 2025). A primary or metastatic malignant neoplasm that affects the colon or rectum. "GA blocked the NF-κB signaling by targeting G protein-coupled receptor 108 (GPR108) in pancreatic and colorectal cancers." (PMID 40900835, 2025).
epilepsy (1 paper, 2024). A brain disorder characterized by episodes of abnormally increased neuronal discharge resulting in transient episodes of sensory or motor neurological dysfunction, or psychic dysfunction. "TRIP10 encodes a cytoskeletal binding protein involved in endocytosis that suppresses glucose uptake in response to insulin signaling, GPR108 encodes an orphan G-protein-coupled receptor, and SIK1 encodes a salt-inducible kinase with roles in cancer, epilepsy, and myeloid signaling." (PMID 39302339, 2024).
multiple sclerosis (1 paper, 2024). A progressive autoimmune disorder affecting the central nervous system resulting in demyelination. "The TRIP10 and GPR108 promoters were each captured in contact with a high-confidence variant rs1077667 (PP > 0.99), which is located in an intron of TNFSF14 and is associated with multiple sclerosis." (PMID 39302339, 2024).
infection (2 papers, 2023 to 2024). The state of being infected such as from the introduction of a foreign agent such as serum, vaccine, antigenic substance or organism. "AAV5 is thought to be GPR108-independent but necessitates AAVR for infection, while AAV4 and related serotypes are AAVR-independent but require GPR108." (PMID 39685843, 2024). "Certain exceptions have been noted, in particular, AAV4 and related isolates, which is known to be AAVR-independent but requires GPR108, while AAV5 is thought to be GPR108-independent but requires AAVR for infection." (PMID 37097176, 2023).
GPR108 also shares sentences with these, for which no sentence is quoted: cancer (1 paper); Psoriasiform dermatitis (1); psoriasis (1).